VIM (vimentin)
Diseases named in the same sentence as VIM in open-access papers (continued):
Sharing a sentence is not in itself a finding about the gene and the disease.
lymphoma (19 papers, 2008 to 2025). A malignant (clonal) proliferation of B- lymphocytes or T- lymphocytes which involves the lymph nodes, bone marrow and/or extranodal sites. "Further, CLP36 silencing repressed the expressions of Cadherin 2 (CDH2) and Vimentin (VIM) yet promoted those of Bax and Caspase 3 in lymphoma cells, concurrent with the reduction on the phosphorylation of PI3K, AKT and CREB, all of which were confirmed to be positively correlated with CLP36." (PMID 39735560, 2024). "Further, the levels of metastasis-related proteins cadherin 2 (CDH2) and vimentin (VIM) were calculated to evaluate the metastasis potential of lymphoma cells, and it was evident that the knockdown of CLP36 led to the diminished levels of these two proteins in lymphoma cells (P < 0.05)." (PMID 39735560, 2024). "It is noteworthy that both the GBM and lymphoma hybrid transplants all retained CD74, CXCR4 and VIM genes, suggesting that these are important to evaluate in other examples of spontaneous fusions of human tumor and rodent host cells." (PMID 23405135, 2013). "All forms of hematological malignancies (lymphoid and myeloid leukemia, multiple myeloma, and lymphomas) show the expression of signatures, like the EMT, due to the uplifting of mesenchymal markers, such as vimentin, which are involved in aggressive tumor behavior." (PMID 39941895, 2025). "In the current study on the proliferation and metastasis potential of lymphoma, it was seen that CLP36 silencing could evidently suppress the proliferation and the expression levels of VIM and CDH2 in lymphoma cells." (PMID 39735560, 2024). "However, other lymphoma markers like CD3, cyclin D1, cytokeratin, epithelial membrane antigen (EMA), vimentin, B-cell lymphoma 2 (BCL2), CD117, CD34, desmin, and smooth muscle actin (SMA) were positive only in 1 case each." (PMID 36511607, 2023). "Immunohistochemical analysis showed strong diffuse positivity for CD99, alongside vimentin, BCL2, Cyclin D1, and C-Kit expression, while markers such as CK7, CK20, S100, and CD34 were negative, effectively ruling out differential diagnoses such as rhabdomyosarcoma, lymphoma, and other SRCTs." (PMID 41466962, 2025). "In our case, tumor cells did not express cytokeratins, vimentin but the expression of CD79a, CD20 and bcl2 protein was clearly positive, which enabled us to retain the diagnosis of lymphoma." (PMID 24319526, 2013). "However, lymphoma cells are usually positive for CD20 and negative for cytokeratin, while MRTs exhibit cytokeratin positivity along with mesenchymal markers such as vimentin." (PMID 40115691, 2025).
esophageal cancer (18 papers, 2011 to 2024). A primary or metastatic malignant neoplasm involving the esophagus. "Silencing of the ONECUT2 and VIM genes through promoter methylation has been observed in bladder tumors, while promoter hypermethylation of the CCNA1 and VIM genes is associated with esophageal cancer." (PMID 38473997, 2024). "Overall, the outcomes of this study implicate that Snail-1 knockdown utilizing siRNA can significantly interrupt esophageal cancer cell migration and reduce metastatic-related factors, vimentin, CXCR4, MMP-9, and induce miR-34a and let-7a in vitro." (PMID 30276140, 2018). "Furthermore, E-cadherin and vimentin were stained with immunofluorescence, and then, esophageal cancer cells were observed with the fluorescence microscope." (PMID 34912457, 2021). "Thus, reducing the levels of V-ATPase would likely suppress migration of esophageal cancer cells by suppressingthe expression of Vimentin and MMP family proteins, which would be applicable for the development of potential therapeutic strategies against ESCC." (PMID 27384996, 2016). "Overexpression of PD-L1 enhances the levels of mesenchymal genes (ZEB1, N-cadherin, and Vimentin), and contributes to the EMT phenotypes of esophageal cancer cells." (PMID 33363153, 2020). "Digestive system tumors such as in esophageal cancer, PVT1 upregulation decreased E-cadherinexpression and increased N-cadherin and vimentin expression, and induced epithelial-to-mesenchymal transition (EMT) process." (PMID 30083911, 2019). "We further found that depletion of V-ATPase V1E1 led to reduced expression of vimentin, MMP2, and MMP7, which are critical for metastasis of esophageal cancer cells." (PMID 27384996, 2016). "Compared with the control group, the outcomes revealed that N-cad, Vimentin, and Slug protein expression levels were remarkably reduced in the IPO5 gene silencing group (P < 0.05), suggesting that IPO5 promotes the occurrence of EMT-induced esophageal cancer." (PMID 36120598, 2022). "SNHG1 in esophageal cancer promotes cell proliferation and EMT (epithelial to mesenchymal transition)-mediated invasion, by down-regulation E-CAD (E-cadherin) and up-regulation VIM (Vimentin) and N-CAD, as well as activation of Notch signaling pathway." (PMID 32318335, 2020). "The expression of EMT markers, namely, the epithelial cell marker E-cadherin and the mesenchymal marker vimentin, in si-PLCE1-transfected Eca109 and EC9706 cells and in the controls were examined using Western blot analysis to investigate whether PLCE1 promotes EMT in esophageal cancer cells." (PMID 26657507, 2016). "If we categorized all the 99 cases of esophageal cancer patients into EMT subgroup (n = 60) and non-EMT subgroup (n = 39) based on the evaluation of E-cadherin as well as Vimentin expression levels." (PMID 35107757, 2022).
keloid (18 papers, 2013 to 2026). An irregularly shaped, elevated mark on the skin caused by deposits of excessive amounts of collagen during wound healing. "Vimentin, which is commonly expressed in soft tissue tumors, is highly expressed in keloid keratinocytes and associated with changes in shape, motility and adhesion properties during EMT." (PMID 31440236, 2019). "In the current study, we observed numerous vimentin-positive cells localized to the BMZ in both keloid scars and normal skin in vivo, in association with apparent gaps in the basement membrane." (PMID 27574697, 2016). "Discontinuities of laminin-332 and integrin α6 BMZ staining were identified in keloid epidermis, and the observed breaks in basement membrane staining were associated with vimentin-positive cells in the basal epidermal layer." (PMID 27574697, 2016). "Next, we measured the expression levels of PGI and vimentin (as a cytoplasmic marker of fibroblasts) in keloid and normal skin tissues." (PMID 41556665, 2026). "Immunohistochemical analysis of keloid tissues indicated that vimentin-expressing fibroblasts in the central zone undergo autophagy and glycolysis at higher levels than those in the marginal zone, which was associated with the expression level of HIF-1α." (PMID 38279232, 2024). "The vascular endothelium in keloid tissues also contains cells that co-express both vimentin and CD31." (PMID 35743263, 2022). "Increased levels of vimentin were reported to serve as a mesenchymal marker, and the frequency of vimentin + epidermal cells was found to be higher in KSs and keloid microvessels than in normal skin." (PMID 36092734, 2022). "Third, the epidermis of keloid tissues has significantly more vimentin+ cells than the epidermis of normal skin." (PMID 35743263, 2022). "qPCR results and immunofluorescence staining of vimentin clearly suggested that keloid dermal fibroblasts exhibit fibrotic phenotypes of skin fibrosis and activation of myofibroblasts." (PMID 33672186, 2021). "In this study, keloid tissue after HBOT demonstrated lower expression levels of vimentin, fibronectin, VEGF, and HIF-1α." (PMID 30024539, 2018). "Expression levels of the mesenchymal cell marker VIM were significantly higher in keloid vs. normal keratinocytes in vitro." (PMID 27574697, 2016). "Expression of vimentin in epithelial cells is a hallmark of EMT, and the significantly elevated expression of VIM in keloid keratinocytes suggests induction of EMT in vitro." (PMID 27574697, 2016). "Further, many of the vimentin-positive cells located near the BMZ in keloid scars, adjacent to gaps in integrin α6 staining, were positive for the melanocyte-specific protein tyrosinase-related protein 1 (TYRP1), indicating these cells are melanocytes." (PMID 27574697, 2016). "Colocalization of the Langerhans cell marker, langerin, with some vimentin-positive cells in keloid scar epidermis was observed, suggesting that many of the vimentin-positive epidermal cells in keloid scars are Langerhans cells." (PMID 27574697, 2016). "Expression of vimentin in the vascular endothelium of keloid tissue was previously suggested as evidence of endothelial-to-mesenchymal transition, which, like EMT, has been proposed to contribute to fibrosis." (PMID 27574697, 2016). "We observed localization of vimentin-positive cells in vessels of both keloid scars and normal skin." (PMID 27574697, 2016). "We observed elevated expression levels of vimentin in keloid scars and increased frequency of vimentin-positive epidermal cells, compared with normal skin." (PMID 27574697, 2016). "First, keloids express high levels of TNF-α and TGF-β and normal keratinocytes cultured with these cytokines causes them to gain a fibroblastic morphology, express the mesenchymal marker vimentin." (PMID 35743263, 2022). "Similarly, epithelial cells from keloid tissues express vimentin and another mesenchymal marker (fibroblast-specific protein 1) and lack E-cadherin expression." (PMID 35743263, 2022).
keloid (continued). "The apparent increase of cells coexpressing vimentin and langerin in the suprabasal layers of keloid epidermis suggests that keloid scars may contain elevated numbers of Langerhans cells." (PMID 27574697, 2016). "Moreover, these vimentin+ cells are located in the reddish inflamed invading edge of the keloids." (PMID 35743263, 2022). "Since keloid formation is associated with cellular infiltration, we first wanted to assess the numbers of two cell populations (cell/mm2 tissue) involved in keloid formation, namely immune cells (CD45+) and fibroblasts (Fibroblast+ (recombinant antibody from Miltenyi Biotec), Vimentin+, CD45-)." (PMID 34502327, 2021). "Although CDH1 gene expression levels are similar between normal and keloid keratinocytes, keloids express decreased protein levels of E-cadherin, in line with cadherin switching from E-cadherin to mesenchymal markers such as N-cadherin, fibronectin-1, vimentin, and cadherin-11." (PMID 31440236, 2019). "In our study, we performed in situ immunohistochemical staining for Vimentin and CD90 on primary cultured keloid fibroblasts." (PMID 38284901, 2024). "Later, several independent research groups successfully isolated keloid-derived mesenchymal-like stem cells (KMLSCs) in adult keloid tissue which expressed the MSC CD markers CD13, CD29, CD44, CD90, fibronectin, and vimentin." (PMID 32085797, 2020). "HBOT significantly decreased the expression levels of vimentin, fibronectin, and HIF-1α, suggesting that HBOT has protective effects against the EMT phenomenon during keloid development." (PMID 30024539, 2018). "While shikonin inhibited scratch closure and IL-6 production in keloid line cells, the mechanism of action is unclear given shikonin failed to impact vimentin expression and had less pronounced impacts on metabolism." (PMID 34143844, 2021). "Additionally, culture of keloid dermal fibroblasts with EGF resulted in decreased expression of FSP-1, α-SMA, and vimentin." (PMID 33672186, 2021). "Interestingly, our results indicated that exogenous EGF alleviated the fibrotic phenotype only in keloid dermal fibroblasts, evident by a significantly decreased gene expression of FSP-1, α-SMA and vimentin, as well as decreased vimentin protein expression." (PMID 33672186, 2021). "In this study, H&E staining showed that the constructed normal skin and keloid scar models (co-cultured with or without monocytes) possessed a fully differentiated epidermis on top of a vimentin-positive, fibroblast-populated dermis." (PMID 31187196, 2019). "In addition, in the PTEN knockdown only group, there was a remarkable increasing for the expressions of vimentin and ALDH1 in keloid keratinocytes, which confirmed the role of PTEN in the invasive phenotype of keloids." (PMID 27596120, 2016). "Besides, in the PTEN knockdown only group, there was a remarkable increasing for the expressions of p-AKT (P < 0.01), vimentin (P < 0.01) and ALDH1 (P < 0.001) in keloid keratinocytes." (PMID 27596120, 2016). "Results of western blot showed an enhanced expression of vimentin and a decreased expression of E-cadherin in miR-21-5p mimic transfected keloid keratinocytes compared with the negative control (P = 0.0151 and P = 0.0206, respectively)." (PMID 27596120, 2016). "As miR-21-5p mimic induced the EMT and stem-like cells phenotype in keloid keratinocytes, to figure out whether keloid keratinocytes with the EMT phenotype also possess stem-like cell signature, double fluorescence staining for CD44 (green) and vimentin (red) was performed." (PMID 27596120, 2016). "Our study demonstrated that keloid keratinocytes underwent a transition from an epithelial to a mesenchymal phenotype in response to HIF-1α, with a marked upregulation in the expression of vimentin and fibronectin, and a decrease in E-cadherin and ZO-1 expression." (PMID 25777304, 2015).
keloid (continued). "In conclusion, our study demonstrates that HIF-1α upregulates vimentin and fibronectin expression and downregulates E-cadherin and ZO-1 expression in keloid keratinocytes under hypoxic conditions, which promotes the EMT process and enhances the invasive capacity of the keloid keratinocytes." (PMID 25777304, 2015).
colorectal tumors (17 papers, 2009 to 2025). "Methylation of the SFRP2, GATA4/5, NDRG4 and VIM promoters in fecal DNA is associated with the presence of colorectal tumors." (PMID 25202404, 2014). "We revealed that 5-FU strongly decreased the expression of E-cadherin and increased the expression of vimentin and N-cadherin in the colorectal tumor tissue, indicating a promotion of the EMT status." (PMID 36827121, 2023). "In colorectal tumor tissues, vimentin protein is abundantly present in the vessel wall, although other mesenchymal cell types such as resident immune cells also express the protein." (PMID 35606362, 2022). "Further, expression of Vimentin in the stroma of colorectal tumors reflect higher malignant potential, poor survival, and disease recurrence in patients with CRC48." (PMID 33500399, 2021). "After flow-sorting, keratin-positive epithelial tumor fractions and vimentin-positive stromal fractions of 14 colorectal tumors were successfully analyzed, of which eight were BRAFp.V600E and six were BRAF wild type." (PMID 24244575, 2013). "In colorectal tumours, increased vimentin expression correlates with the presence of oncogenic KRAS and with nuclear beta-catenin." (PMID 19367286, 2009). "However, Sanguisorba officinalis L. impairs nuclear translocation of β-catenin to diminish N-cadherin, vimentin and Snail levels, and enhance E-cadherin levels in increasing 5-flourouracil sensitivity in colorectal tumor." (PMID 38334836, 2024). "In the present study, we demonstrated that introduction of Tiam1 into the germ-line caused a significant increasing of nuclear accumulation of β-Catenin, decreasing of membrane E-Cadherin, and enrichment of Vimentin in the colorectal tumors with more invasive ability." (PMID 24069171, 2013). "Among the IHC biomarkers expressed in colorectal tumors, FAP, α-SMA, VIM, S100A4, PDGFR-α/β, and POSTN were reported in a general review addressing the question of the significance of CAFs in tumor progression and metastasis." (PMID 41450913, 2025). "Decrease in N-cadherin and vimentin levels, and increase in E-cadherin levels can be observed after administration of β-elemene in inhibiting EMT in colorectal tumor." (PMID 38334836, 2024). "To examine the relationship between the E-cadherin/Vimentin and PRL-3 expression in colorectal tumor and liver metastasis specimens, we performed IHC analyses of 75 human colorectal tumors." (PMID 34147083, 2021). "The Western blot analysis results showed that colorectal tumor tissues from F. nucleatum (F01)-treated mice expressed higher levels of LC3-II, Beclin1 and Vimentin and lower levels of P62 and E-cadherin than those from control mice." (PMID 31903123, 2020). "Furthermore, HMGA2‐siRNA delivery by CMD‐CS nanoparticles suppresses metastasis of colorectal tumor cells via down‐regulating MMP‐9 and vimentin, and upregulating E‐cadherin that are beneficial in enhancing DOX cytotoxicity." (PMID 36684100, 2023). "Furthermore, Western blot analysis showed that colorectal tumor tissues from CARD3-/- mice expressed lower levels of LC3-II, Beclin1 and Vimentin and higher levels of E-cadherin than tumor tissues from CARD3wt mice (P < 0.05)." (PMID 31903123, 2020). "However, corresponding liver, lymph node, brain and lung metastases did not express vimentin, indicating other pathways in secondary colorectal tumours." (PMID 19367286, 2009). "Furthermore, data of immunohistochemical analysis demonstrated that baicalin treatment in vivo enhanced the expression of E-cadherin and reduced the expressions of Ki67, Vimentin, N-cadherin, CD133 and CD44 by comparing with negative control in HCT116 orthotopic transplanted colorectal tumors." (PMID 32127957, 2020).